CS (citrate synthase)
Diseases named in the same sentence as CS in open-access papers (continued):
Sharing a sentence is not in itself a finding about the gene and the disease.
autism spectrum disorder (1 paper, 2017). A spectrum of developmental disorders that includes autism, and Asperger syndrome. "We examined citrate synthase and Complex I and IV activities using a validated buccal swab method in 127 children with autism spectrum disorder with and without mitochondrial disease, a portion of which were on common mitochondrial supplements." (PMID 28208802, 2017).
avian influenza (1 paper, 2022). Infection of domestic and wild fowl and other birds with influenza A virus. "In addition, using flagellin as an adjuvant and co-mixing with mycobacterial protein Ag85B, avian influenza H5N1 antigen, and Plasmodium falciparum CS protein, improves the immunogenicity of these antigens and induces specific IgG antibodies against these antigens." (PMID 35953794, 2022).
brain injury (1 paper, 2013). Acute and chronic (see also brain INJURIES, CHRONIC) injuries to the brain, including the cerebral hemispheres, CEREBELLUM, and brain STEM. "However, despite constant mitochondrial density, citrate synthase activity decreased in ventral ON at day 7, perhaps due to the demonstrated inhibition of this enzyme by alkyl peroxyl and alkoxyl radicals, which are elevated following traumatic brain injury." (PMID 24011177, 2013).
breast tumor (1 paper, 2022). "The reduction in acetylation loosens the interaction between fumarase (FH)-MDH2-citrate synthase (CS) complex, which reduces TCA flux and finally limits breast tumor growth." (PMID 35625948, 2022).
celiac disease (1 paper, 2017). An autoimmune genetic disorder with an unknown pattern of inheritance that primarily affects the digestive tract. "This SNP lies in the CS gene (citrate synthase), and the gene has been previously associated with psoriasis, height and celiac disease." (PMID 28931044, 2017).
colitis (1 paper, 2025). Inflammation of the colon. "In a DSS-induced colitis model, we observed that activation of the HMGB1/TLR4/NF-kB pathway resulted in decreased GPX4 expression, accompanied by increased mRNA levels of ferroptosis-related indicators (PTGS2, IREB2, CS, RPL8, and ATP5G3), which was further verified by cellular experiments." (PMID 40689397, 2025).
colon adenocarcinoma (1 paper, 2022). "To translate our findings to human cancer, we analyzed The Cancer Genome Atlas RNA-Seq data and identified a highly significant positive correlation between FASN and CS gene expression in human colon adenocarcinomas." (PMID 35742953, 2022). "In summary, these data suggest that CS is highly expressed in CRC, and there is a positive correlation between CS and FASN expression at mRNA and protein levels in colon adenocarcinomas." (PMID 35742953, 2022).
Crohn disease (1 paper, 2017). A gastrointestinal disorder characterized by chronic inflammation involving all layers of the intestinal wall, noncaseating granulomas affecting the intestinal wall and regional lymph nodes, and transmural fibrosis. "Using a single-blind case-control design, complex I and IV and citrate synthase activities and complex I-V protein quantity from 10 children with ASD, 10 children with Crohn’s disease and 10 neurotypical children with nonspecific GI complaints were measured." (PMID 29028817, 2017).
cyst (1 paper, 2020). A sac-like closed membranous structure that may be empty or contain fluid or amorphous material. "Because of these functions, the CS might be involved in the regulation of energy supply required for the cyst formation." (PMID 32225121, 2020).
Encephalopathy (1 paper, 2023). Encephalopathy is a term that means brain disease, damage, or malfunction. "However, a high content of H2S can lead to a decrease in the activity of citrate synthase (CS) and aconitase (Aco) in the mitochondria of neurons of the cerebral cortex, as well as creatine kinase (CK) in this brain structure, the striatum, and the hippocampus in encephalopathy." (PMID 37445920, 2023).
Hepatic steatosis (1 paper, 2016). Steatosis is a term used to denote lipid accumulation within hepatocytes. "HSP72 may function to activate fatty acid oxidation as a result of activation of CS and β-HAD in liver and muscle, thereby reducing hepatic steatosis." (PMID 27759092, 2016).
Hyperammonemia (1 paper, 2021). An increased concentration of ammonia in the blood. "Mitochondrial oxidative dysfunction during hyperammonemia was not accompanied by changes in mitochondrial content (citrate synthase, and outer membrane protein and voltage dependent anion channel [VDAC] expression) in myotubes or rat skeletal muscle." (PMID 34935641, 2021).
hypothyroidism (1 paper, 2015). Abnormally low levels of thyroid hormone. "To assess whether hypothyroidism and T2 administration to Hypo rats might affect BAT mitochondrial density, we evaluated: mitochondrial content (expressed as mitochondrial protein/100 mg tissue), COX activity, citrate synthase, VDAC1 content and COX IV immunohistochemistry." (PMID 25658324, 2015).
infantile epilepsy (1 paper, 2016). "The older child presented with infantile epilepsy and developed Parkinsonian symptoms in her teens, with reduced complex I activity at 29% of the control mean (0.030 nmols NADH oxidized/min per unit of citrate synthase, control mean 0.104 ± 0.036)." (PMID 27069701, 2016).
infarction (1 paper, 2020). A localised pathological necrosis of tissue resulting from obstruction of the blood supply usually by a thrombus, an embolus, or vascular torsion. "Infarction decreased the activity of citrate synthase and reduced the activity of complexes I and II, and the supplementation did not interfere in this variable." (PMID 32468694, 2020).
lactic acidosis (1 paper, 2020). Metabolic acidosis characterized by the accumulation of lactate in the body. "The diminished mRNA levels of HIF-1α correlated with an increased expression of citrate synthase, alongside with the increase of mitochondrial respiration rate in A-427 cells cultured under lactic acidosis and normoxia; nonetheless, HIF-1α protein levels presented a slight increase." (PMID 32596143, 2020). "To figure out how the metabolism of tumor and fibroblast cells was regulated under lactic acidosis, we evaluated AMPK, HIF-1α, and CS transcript levels on these cells after 48 h of incubation under the four culture conditions." (PMID 32596143, 2020).
latent infection (1 paper, 2012). "Of these, only GltA1, which encodes a metabolic enzyme called citrate synthase, had generally high enough expression levels for reliable quantification from fish with a latent infection." (PMID 23028333, 2012).
lipid metabolism disorders (1 paper, 2021). "This study demonstrated the crucial roles played by the miR-33-5p/ABCA1/CS axis in regulating cholesterol efflux, inflammation, apoptosis, and aging in VECs, and also suggested the axis as a target for managing lipid metabolism disorders." (PMID 34517822, 2021). "However, there have been no reports of CS activity being associated with cholesterol efflux or lipid metabolism disorders such as atherosclerosis or CVD." (PMID 34517822, 2021). "Furthermore, as MMP-9 has been shown to cleave citrate synthase ex vivo, the change and involvement of MMP-9 in lipid metabolism disorders should also be further investigated, along with the role played by the miR-33-5p/ABCA1/CS axis." (PMID 34517822, 2021).
lipodystrophy (1 paper, 2018). A congenital or acquired disorder characterized by abnormal loss or redistribution of the adipose tissue in the body. "Patients with HIV-lipodystrophy display impaired fat oxidation and two recent studies show impaired mitochondrial oxidative phosphorylation and activity of enzymes involved in fat oxidation; e.g. β-HAD and citrate synthase in skeletal muscle in HIV patients." (PMID 29342149, 2018).
liver cancer (1 paper, 2025). An epithelial or non-epithelial malignant neoplasm that arises from the liver. "This study found that the level of succinylation of CS is elevated in human liver cancer tissues, and the expression of CS protein is significantly increased." (PMID 40557149, 2025). "In this study, we found that the CS K346R mutant, which simulates the desuccinylation of CS, resulted in decreased CS enzyme activity, significantly reduced mitochondrial activity and ATP levels, increased ROS levels, and markedly inhibited the proliferation of liver cancer cells." (PMID 40557149, 2025). "Moreover, ROC analysis demonstrated that the expression of CS and SIRT5 could distinguish HCC from normal tissue with high accuracy, thereby reinforcing the rationale for exploring their mechanistic interplay in mitochondrial metabolism and apoptosis regulation in liver cancer cells." (PMID 40557149, 2025).
lung adenocarcinoma (1 paper, 2019). A carcinoma that arises from the lung and is characterized by the presence of malignant glandular epithelial cells. "eIF3i, HSC71, MHC class I antigen, transketolase, citrate synthase, Rab-37, MLH1 and AGR2 might be putative biomarkers in HSP90 inhibition response in lung adenocarcinoma." (PMID 31370342, 2019).
malnutrition (1 paper, 2021). Inadequate nutrition resulting from poor diet, malabsorption, or abnormal nutrient distribution. "The levels of mitochondrial enzymes, that is, CS and SDH activities, and expression of COX IV protein, decreased in both plantaris and soleus muscles of the malnutrition group." (PMID 33650806, 2021). "In addition, malnutrition resulted in a decrease in the expression levels of PGC‐1α and PINK protein, and induced a decrease in the levels of two key mitochondrial enzymes (succinate dehydrogenase and citrate synthase) and COX IV protein expression in both muscles." (PMID 33650806, 2021).
muscle disorder (1 paper, 2024). "Finally, APLS, CS, TA, GPA (that are blood vessel disorders) and MY diseases were located at the top of the PC2 axis, in a C3 disease cluster, with MY (that is a muscle disorder) being at the extreme top of the PCA (PC2-C3)." (PMID 38182406, 2024).
nasopharyngeal carcinoma (1 paper, 2025). A carcinoma arising from the nasopharyngeal epithelium. "In nasopharyngeal cancer, miR-122–5p modulates citrate synthase (CS) and GSH levels, promotes ferroptosis, and may influence tumor growth and treatment response." (PMID 40403492, 2025).
non-small cell lung carcinoma (1 paper, 2022). A group of at least three distinct histological types of lung cancer, including non-small cell squamous cell carcinoma, adenocarcinoma, and large cell carcinoma. "CS, an enzyme of the tricarboxylic acid cycle, has been recognized as an important factor in the progression of cancer pathogenesis and was found to be a marker of chemoresistance in non-small-cell lung carcinoma." (PMID 35512017, 2022).
osteoarthritis (1 paper, 2017). A noninflammatory degenerative joint disease occurring chiefly in older persons, characterized by degeneration of the articular cartilage, hypertrophy of bone at the margins and changes in the synovial membrane. "Gene network analysis revealed complex interactions of CS gene products, data compatible with the hypothesis that CS genes are functionally related in the initiation and progression of complex diseases such as osteoarthritis." (PMID 29262782, 2017).
ovarian tumors (1 paper, 2021). "Relative to benign tissue, ovarian tumors exhibited a striking 8.4-fold higher CS activity, 3.3-fold higher SDH activity, and a 8.2-fold higher COX activity, but a similar (3.1% lower, N.S.)mtDNAcn." (PMID 34078919, 2021).
overnutrition (1 paper, 2025). An imbalanced nutritional status resulting from excessive intake of nutrients. "In relation to mitochondrial function, we assessed the activity of citrate synthase, a key enzyme in the oxidative system that initiates the reactions of the citric acid cycle; our findings indicated that overnutrition adversely affected the activity of this enzyme in the hypothalamus." (PMID 40452918, 2025).
Pearson syndrome (1 paper, 2022). Pearson syndrome is characterized by refractory sideroblastic anemia, vacuolization of bone marrow precursors and exocrine pancreatic dysfunction. "We observed that citrate synthase activity, used as a marker of mitochondrial mass, was significantly increased in Pearson syndrome fibroblasts, but not altered or even decreased in Pearson syndrome iPSCs and cybrids." (PMID 35191981, 2022). "Different tendencies observed among Pearson syndrome cell models demonstrated that a drop in OXPHOS parameters would not depend on mitochondrial mass, so citrate synthase activity was not used to normalise them, although it could limit the interpretation of results." (PMID 35191981, 2022).
periodontitis (1 paper, 2012). An acute or chronic inflammatory process that affects the tissues that surround and support the teeth. "Recently, our group described that PBMCs from patients with periodontitis have a mitochondrial dysfunction characterized by lower CoQ10 levels and citrate synthase activity, together with high levels of ROS production." (PMID 23075094, 2012).
potassium deficiency (1 paper, 2021). A condition due to decreased dietary intake of potassium, as in starvation or failure to administer in intravenous solutions, or to gastrointestinal loss in diarrhea, chronic laxative abuse, vomiting, gastric suction, or bowel diversion. "For example, the Arabidopsis CS mutant gso1/sgn3 displayed a severe potassium deficiency phenotype under low potassium conditions." (PMID 34206144, 2021).
preeclampsia (1 paper, 2026). Preeclampsia is a hypertensive disorder of pregnancy that is characterized by new-onset hypertension with proteinuria presenting after 20 weeks of gestation, and depending on mild or severe forms may initially present with severe headache, visual disturbances, and hyperreflexia. "In conclusion, preeclampsia is associated with mitochondrial dysfunction and increased CoQ10 levels normalized to CS activity, specifically in cytotrophoblast mitochondria, with findings being consistent with a possible involvement of mitophagy in this cell type." (PMID 41594874, 2026).
progerias (1 paper, 2024). "Further, tools such as this can identify patterns not previously recognized in known progerias, for instance we observe that XPA, CS and AT cluster closely together while XPB and XPG that in rare cases can lead to a CS like phenotype are in a separate, but associated, cluster." (PMID 38345566, 2024).
pseudotuberculosis (1 paper, 2019). "Hence, VYp CS-Ypst and VYpst D255N did not confer any protection against pseudotuberculosis." (PMID 31428104, 2019).
retinoblastoma (1 paper, 2021). A malignant tumor that originates in the nuclear layer of the retina. "To do this, we measured the levels of TCA protein, Citrate Synthase (CS), in six Retinoblastoma tumor samples and three normal retinal controls." (PMID 34404904, 2021).
Sengers syndrome (1 paper, 2015). Congenital cataract - hypertrophic cardiomyopathy - mitochrondrial myopathy (CCM) is a mitochondrial disease characterized by cataracts, hypertrophic cardiomyopathy, muscle weakness and lactic acidosis after exercise. "Accordingly, laboratory analyses of patients affected by Sengers syndrome revealed shifts in the activity of respiratory chain complexes and citrate synthase, consequently effecting mitochondrial ATP synthesis." (PMID 26552583, 2015).
septic shock (1 paper, 2014). Shock caused by infection; frequently caused by gram negative bacteria, although some cases have been caused by other bacteria, viruses, fungi, and protozoa; characterized by fever, chills, tachycardia, tachypnea, and hypotension. "On day one, platelets of patients with septic shock had lower NADH, complex I, complex I and III and complex IV (relative to citrate synthase) activities and higher citrate synthase activity than controls." (PMID 24787741, 2014).
spinal disease (1 paper, 2021). "One attempt to clarify this was recently reported, where authors evaluated both bulbar and spinal disease in SOD1G93A mice through the study of the citrate synthase (CS), among other markers." (PMID 33450997, 2021).
Stroke (1 paper, 2016). Sudden impairment of blood flow to a part of the brain due to occlusion or rupture of an artery to the brain. "Stroke significantly impaired the activity of OXPHOS and complex IV (cytochrome c oxidase) of the mitochondrial respiration chain and reduced the respiratory control ratio (RCR) and citrate synthase activity." (PMID 27902774, 2016).
TCA cycle disorders (1 paper, 2014). "Combining lentivirus-shRNA transduction with lysine treatment in the primary neurons further reduced the gene expression of PDC and CS, which demonstrated that GCDH gene silencing can cause TCA cycle disorders." (PMID 25333616, 2014).
UV-sensitive syndrome (1 paper, 2016). UV-sensitive syndrome is a condition that is characterized by sensitivity to the ultraviolet (UV) rays in sunlight. "Certain mutations in the CS genes can also give rise to the clinically less severe UV-sensitive syndrome (UVSS)." (PMID 26972010, 2016).